LOX (lysyl oxidase)
Diseases named in the same sentence as LOX in open-access papers (continued):
Sharing a sentence is not in itself a finding about the gene and the disease.
liver fibrosis (38 papers, 2015 to 2026). "Within the setting of the liver, fibrosis is correlated with increased LOX levels in both the tissue and serum of patients, and there is a further association with altered collagen in the extracellular space in animal models of hepatic fibrosis." (PMID 35205728, 2022). "Increased LOX activity is associated with fibrotic diseases such as lung and liver fibrosis and atherosclerosis, whereas decreased LOX activity is associated with lathyritic agent-induced emphysema in animal models and with disorders of copper metabolism like Menkes syndrome." (PMID 27367711, 2016). "There is emerging evidence that lysyl oxidase and related proteins may be implicated in the development of hepatic fibrosis." (PMID 28030556, 2016). "Other enzymes, such as LOX and TG, are also upregulated during liver fibrosis, promoting protein cross-linking and/or stabilization of ECM proteins (e.g., collagen I or fibronectin), increasing their resistance to proteolytic degradation." (PMID 40371390, 2025). "The inhibition of LOX suppressed the cross-linking of collagen and attenuated CCl4-induced advanced hepatic fibrosis." (PMID 36711017, 2023). "The stellate cells and portal fibroblasts were the major cellular sources of LOXs in CCl4-induced model of liver fibrosis, and LOX-mediated deoxypyridinoline and pyridinoline cross-links increased correspondingly with liver stiffness." (PMID 36711017, 2023). "HIF-1α is capable of regulating the release of lysyl oxidase (LOX), an enzyme that crosslinks extracellular matrix proteins and promotes liver fibrosis in NASH." (PMID 37850091, 2023). "Elevated LOX levels in patient serum have since been mapped along the liver fibrosis continuum from chronic persistent hepatitis to chronic active hepatitis to cirrhosis." (PMID 35205728, 2022). "Intriguingly, microRNAs (miRNAs) that have been found to target LOX/LOXLs have been identified in liver fibrosis." (PMID 35205728, 2022). "Another animal study demonstrated antifibrotic effect of BPAN through reducing collagen fiber bundles and LOX level, which indicates its potential role in attenuating the development of liver fibrosis." (PMID 35311155, 2022). "For example, in renal and liver fibrosis increased LOX expression leads to ECM production and progression of fibrosis." (PMID 36408252, 2022). "Allysine (α-aminoadipic-δ-semialdehyde), abundantly produced by lysyloxidase (LOX) during liver fibrosis, is a reliable pathological marker 36–38." (PMID 32218438, 2020). "The members of LOX family are therapeutic targets for liver fibrosis indeed, mostly LOX, LOXL1, and LOXL2." (PMID 33383846, 2020). "Inhibition of all LOX members by β-aminopropionitrile decreased number and activity of MFs leading to a lower degree of liver fibrosis in this CCl4 induced liver fibrosis mouse model." (PMID 32260126, 2020). "A previous study performed in a model of TAA-induced experimental liver fibrosis has explored the specific contribution of LOX and LOXL2 to fibrotic matrix stabilization utilizing specific blocking mAbs (M64 and AB0023, respectively)." (PMID 32296422, 2020). "Development of liver fibrosis in a CCl4 based mouse model was shown to be accompanied by a 30-fold increase in LOX activity." (PMID 32260126, 2020). "The treatment of LOX inhibitor β-aminopropionitrile (BAPN) decreases collagen stability during liver fibrosis progression and facilitates fibrosis reversal after CCl4-induced advanced liver fibrosis." (PMID 31754325, 2019). "Liu and colleagues 31 found that LOX had the functional contribution to stabilize collagen in liver fibrosis progression or reversal." (PMID 31754325, 2019). "The implications of LOX have been previously studied for several human fibrotic disorders, e.g., kidney fibrosis, liver fibrosis and oral submucous fibrosis." (PMID 29866167, 2018).
liver fibrosis (continued). "The treatment of BAPN with mice in carbon tetrachloride- (CCl4-) induced liver fibrosis facilitates fibrosis reversal after CCl4 withdrawal, supporting the concept of pharmacologic targeting of LOX pathway to inhibit liver fibrosis and promote its resolution." (PMID 27800489, 2016). "Taken together, our results suggest that fibulin‐4, essential for lysyl oxidase activation, might be a new liver fibrosis marker found in the sEVs of patients with cirrhosis." (PMID 38853023, 2024). "The accumulated evidence that LOX/LOXL activity plays important roles in liver fibrosis suggests that targeting these may have potential therapeutic benefit by reducing fibrosis." (PMID 35205728, 2022). "In addition to LOX, links between liver fibrosis and LOXLs have also been identified, spanning non-alcoholic fatty liver disease (NAFLD) to cirrhosis." (PMID 35205728, 2022). "The expression of LOX is upregulated in several fibrotic diseases associated with an accumulation of collagen and ECM components, such as pulmonary fibrosis, skin tissues, hepatic fibrosis and cardiac fibrosis." (PMID 35160252, 2022). "In addition, RES reduced collagen fiber bundles, hydroxyproline, and lysyl oxidase (LOX) to alleviate liver fibrosis." (PMID 32382557, 2020). "Noteworthy, LOX is discussed as a serum biomarker of liver fibrosis in patients with NAFLD." (PMID 31718044, 2019). "It has been demonstrated that Zn could prevent hepatic fibrosis by inhibiting lysyl oxidase which is involved in the intermolecular cross-linkage of collagen." (PMID 30210344, 2018). "We hypothesized that liver hypoxia in this NAFLD model would lead to HIF-1 activation, and enhanced liver fibrosis via LOX upregulation." (PMID 28030556, 2016). "While the role of hydroxylysine and allysine have yet to be elucidated in pCAVS or fibrocalcific CAVS, inhibition of lysyl oxidase inhibitors may be an additional potential therapeutic strategy, with promising results shown related to fibroblast activation in liver fibrosis." (PMID 36439995, 2022). "MicroRNA-29a (MIR29A) has been shown to exert a hepatoprotective effect on hepatocellular damage and liver fibrosis induced by cholestasis and diet stress, while its clinical and biological role on the activity hypoxia responsive genes including LOX, LOXL2, and VEGFA remains unclear." (PMID 34206143, 2021). "Additionally, we have shown that in bariatric patients, serum LOX is elevated in patients with NAFLD-associated hepatic fibrosis, relative to those without fibrosis." (PMID 28030556, 2016). "Under hypoxic conditions, HIF-1α enhances collagen and elastin expression by targeting lysyl oxidase (LOX), thereby increasing the stiffness and stability of ECM and promoting liver fibrosis." (PMID 40242037, 2025). "LOX proteins (LOX, LOXL1, LOXL2, LOXL3, and LOXL4) are extracellular copper‐dependent enzymes and have been identified as potential therapeutic targets in liver fibrosis." (PMID 38853023, 2024). "Previous studies found that expression of LOX, LOXL1, and LOXL2 are increased in patients with liver fibrosis." (PMID 36711017, 2023). "LOX secreted by HCC promotes tube formation of endothelial cells through upregulation of VEGF, and overexpressed LOX increases angiogenesis, whereas LOXL1 was found to be increased in liver fibrosis models." (PMID 35311155, 2022). "Also, zinc may inhibit hepatic fibrosis by reducing the activity of lysyl oxidase." (PMID 34623551, 2021). "Many of these genes, including COL1A1, LOX, MMP14, TGFB3, TIMP1 and VCAN, are known markers for liver fibrosis." (PMID 34588551, 2021). "A later study showing rapid downregulation of LOXL2 after liver injury in contrast to stable upregulation of LOX and LOXL1, suggests a rather minor role of LOXL2 in liver fibrosis." (PMID 32260126, 2020). "β-aminopropionitrile (BAPN), an irreversible LOX inhibitor, inhibited HSC activation and amplified fibrosis reversion in a CCl4 mouse model of liver fibrosis." (PMID 31718044, 2019).
liver fibrosis (continued). "In addition, Cu could promote hepatic fibrosis by acting as a cofactor of lysyl oxidase." (PMID 30210344, 2018). "The treatment of LOX inhibitor BAPN decreases collagen stability during liver fibrosis progression and facilitates fibrosis reversal after CCl4-induced advanced liver fibrosis." (PMID 27800489, 2016). "CDCA also reduced hypoxic induction of other HIF-1α target genes such as lysyl oxidase (LOX) and collagen prolyl-4 hydroxylase A1 (P4HA1) which are involved in hepatic fibrosis." (PMID 26098428, 2015). "Lysyl oxidase (LOX) converts lysine molecules into highly reactive aldehydes that form the cross‐links of ECM proteins and promote cross‐linking and stabilization of collagens during liver fibrosis." (PMID 36999514, 2023). "Therefore, dysfunction of LOX and the LOXL family contributes to various types of diseases including liver fibrosis, cardiovascular disease, and cancer." (PMID 31921422, 2020). "On the other hand, TG2−/− mice have normal collagen crosslinking and are not protected from liver fibrosis, suggesting that the lysyl oxidase (LOX) family has a role in disease progression." (PMID 30200219, 2018). "In addition, LOX and LOXL2 were also found to be elevated in liver fibrosis and were associated with increased deposition of collagen around the hepatocytes." (PMID 29125826, 2017). "Indeed, the pan-LOX inhibitor PXS-5505 and the LOXL2/3 inhibitor PXS-5153A have been proven to have anti-hepatic fibrosis properties, among which PXS-5505 is currently undergoing clinical trials (NCT04676529), indicating that LOX is still a target worth developing to treat fibrosis." (PMID 40492139, 2025). "LOX and LOXL inhibition by the non-selective inhibitor BAPN decreased liver stiffness and liver HSC/myofibroblast activation, paralleled by a reduction in the number of α-SMA positive cells in rodent models of liver fibrosis." (PMID 41385725, 2026). "Patients with liver fibrosis had higher baseline LOX than those without fibrosis; meanwhile, serum LOX was higher in patients with severe OSA than in healthy subjects; however, the level of serum LOX decreased after treatment with continuous positive airway pressure (CPAP) in patients with OSA." (PMID 37850091, 2023).
pulmonary fibrosis (35 papers, 2013 to 2026). Chronic progressive interstitial lung disorder characterized by the replacement of the lung tissue by connective tissue, leading to progressive dyspnea, respiratory failure, or right heart failure. "LOX has been found to be increased in lung fibroblasts of SSc patients and in a murine model of pulmonary fibrosis, suggesting its direct pathogenic role in SSc-associated fibrosis." (PMID 36014018, 2022). "In vivo, romidepsin inhibited bleomycin-induced pulmonary fibrosis in association with suppression of LOX expression." (PMID 28467787, 2017). "Here we identify aberrant YAP/TEAD/LOX signaling in fibrotic alveolar cells as a central mechanism in pulmonary fibrosis onset and progression." (PMID 40753090, 2025). "Pharmacological YAP inhibition via verteporfin reverses fibrotic alveolar type II cell reprogramming and LOX expression in experimental lung fibrosis in vivo and in human fibrotic tissue ex vivo." (PMID 40753090, 2025). "First, we utilized BAPN to inhibit LOX in a real-time collagen assembly assay utilizing BALF from a murine model of pulmonary fibrosis." (PMID 40753090, 2025). "Upregulation of lysyl oxidase has been identified from the fibrotic lesion in lung fibrosis patients and in bleomycin-induced lung fibrotic injury." (PMID 38509574, 2024). "LOX blood levels and their variations have been proposed as tentative biomarkers of lung fibrosis activity at both the preclinical and clinical stages." (PMID 39407979, 2024). "Lysyl oxidase (LOX) in lung megakaryocytes cross-links collagen and elastin, promotes extracellular matrix accumulation, and aggravates pulmonary fibrosis." (PMID 38902986, 2024). "Previous research has demonstrated that the activation of lysine‐specific demethylase 1 contributes to lung myofibroblast differentiation and fibrosis, and lysyl oxidase promotes bleomycin‐induced pulmonary fibrosis via modulating inflammation." (PMID 39424430, 2024). "This study demonstrates that PXS-5505 inhibits activity of lysyl oxidase in the lung, reduces bleomycin-induced increases in collagen, elastin and their cross-links and thereby ameliorates lung fibrosis." (PMID 35628342, 2022). "In a murine model of bleomycin lung fibrosis, serum LOX levels were used as a biomarker of response to therapy." (PMID 36359382, 2022). "Crosslinking of matrix components, such as collagen and elastin, through the conversion of lysine moieties to aldehydes by the enzyme LOX, reduces matrix proteolysis in skin and lung fibrosis." (PMID 36359382, 2022). "Upregulation of LOX and LOXL2 has been implicated in several pathologies, including cancer, cardiac fibrosis, idiopathic pulmonary fibrosis, vascular stiffening in aging, and pulmonary hypertension." (PMID 34226627, 2021). "We observed a similar finding in a pulmonary fibrosis study where as the fibrosis (scar) matured, the allysine levels and LOX activity declined but hydroxyproline values remained elevated." (PMID 33731798, 2021). "Collagen crosslinking mediated by the lysyl oxidase family of enzymes (LOX, LOXL1-4) contributes to the pathogenesis of idiopathic pulmonary fibrosis (IPF), a progressive scarring lung disease which predisposes patients to lung cancer, mostly NSCLC." (PMID 33114183, 2020). "Conversely, ectopic LOX sensitizes fibrosis-resistant mice to inflammation and bleomycin-induced lung fibrosis and is critical for the progression of lung fibrosis by enhancing the inflammatory response." (PMID 32708046, 2020). "For example, targeting LOX has been shown to reduce peritoneal fibrosis cardiac fibrosis and pulmonary fibrosis." (PMID 30374330, 2018). "In summary, we provide the first systematic comparison of lysyl oxidase expression in experimental and clinical pulmonary fibrosis and their functional involvement in fibroblast to myofibroblast transition in vitro." (PMID 28273952, 2017).
pulmonary fibrosis (continued). "Using 2D and 3D culture models, as well as an in vivo model of pulmonary fibrosis, romidepsin suppressed interstitial collagen production as well as expression of LOX, whose activity is required for collagen cross-linking." (PMID 28467787, 2017). "Immunohistochemistry demonstrated that enhanced LOX expression in bleomycin-induced lung fibrosis was significantly attenuated in TNC−/− mice." (PMID 27256716, 2016). "In a tumor-unrelated in vivo model of pulmonary fibrosis, we recently observed that LOX expression is increased in fibrotic lungs induced by both irradiation and bleomycin." (PMID 25052686, 2014). "Irradiation of lung tissue created LOX-dependent collagen crosslinking and subsequent lung fibrosis with a growth-permissive fibrotic microenvironment supporting metastatic growth." (PMID 25052686, 2014). "In our current study, we targeted the distal YAP-TEAD LOX axis using multiple distinct approaches which together strongly supports a role for distal epithelial-derived LOX in altered collagen assembly in the parenchyma in pulmonary fibrosis." (PMID 40753090, 2025). "Enhanced LOX expression or activity is a valuable marker of lung fibrosis progression." (PMID 39407979, 2024). "Regardless of the issues associated with targeting LOXL2 in pulmonary fibrosis, caution is certainly warranted as biotech and pharmaceutical Companies proceed with other targeting approaches toward LO and LOX and simply rely on preclinical data from bleomycin-induced pulmonary fibrosis models." (PMID 38873180, 2023). "LOX inhibition using nordihydroguaiaretic acid has been shown to attenuate bleomycin induced lung fibrosis, which suggests that bleomycin may exert its pulmonary toxic activity through dysregulating lipid metabolism." (PMID 35448520, 2022). "Utilizing lipidomics could provide insight as to which LOX metabolites are critical for preventing drug induced lung fibrosis." (PMID 35448520, 2022). "Increased levels of LOX have been found in the tissue fibrosis of various organs with excessive remodeling (e.g., in mice after myocardial infarction; in patients with systemic sclerosis; and in patients with idiopathic pulmonary fibrosis)." (PMID 34769331, 2021). "LOX modulation of TGF-β signaling also occurs in idiopathic pulmonary fibrosis." (PMID 32708046, 2020). "Increased LOX activity and expression has been found in e.g. skin and lung fibrosis." (PMID 24622053, 2014). "However, LOX activity is increased in fibrotic lung diseases such as idiopathic pulmonary fibrosis but decreased in COPD, another inflammatory obstructive disorder of the airways, and LOX-deficient mice develop abnormal formation of bronchi with thick airway walls." (PMID 34836256, 2021). "Therefore, to deepen our understanding of the function of LOX/LOXL in pulmonary fibrosis, we performed a systematic comparison of the LOX/LOXL family members by combining expression analyses in lung tissue samples and primary human lung cells with functional siRNA studies in human lung fibroblasts." (PMID 28273952, 2017). "To this end, we demonstrated that YAP inhibition, using either a pharmacological compound (VP) or siRNA-mediated knockdown, reduces LOX expression in AT2 cells in vitro, experimental lung fibrosis in vivo, and human lung fibrosis modeled in PCLS ex vivo." (PMID 40753090, 2025). "Here, the authors discover that YAP-TEAD/LOX axis is activated in distal lung epithelial cells, which contributes to ECM remodeling in pre-clinical models of pulmonary fibrosis." (PMID 40753090, 2025). "Triptolide inhibited of IKKβ/NF-κB-mediated lysyl oxidase (LOX) production to reduce profibrotic IL-1β, IL-13 and TGF-β to diminish radiation-induced pulmonary fibrosis, and to improve mouse survival following radiation." (PMID 36700235, 2022). "Numerous studies on bleomycin-induced lung fibrosis have confirmed the induction of LOX expression and the amelioration of fibrosis by the pan-lysyl oxidase inhibitor β-aminopropionitrile (BAPN)." (PMID 35205728, 2022).